DENND2D (DENN domain containing 2D)
Description:
Guanine nucleotide exchange factor (GEF) which may activate RAB9A and RAB9B. Promotes the exchange of GDP to GTP, converting inactive GDP-bound Rab proteins into their active GTP-bound form.
Synonyms: FLJ22457; RP5-1180E21.2
Tractability: PROTAC: ubiquitination databases record sites on it; its protein half-life has been measured.
Gene: Protein-coding gene on chromosome 1 (111,185,969 to 111,204,535, reverse strand). Ensembl gene ENSG00000162777.
Subcellular location: Cytoplasm
Subcellular location (Human Protein Atlas): Cytosol; Nucleoplasm
Pathways (Reactome):
Vesicle-mediated transport: RAB GEFs exchange GTP for GDP on RABs
Gene Ontology:
Molecular function: guanyl-nucleotide exchange factor activity; protein binding
Cellular component: cytosol; cytoplasm
Genetic constraint (gnomAD): Loss-of-function variants: 37 observed, 61.99 expected, observed/expected ratio (o/e) 0.6, 90% interval 0.46 to 0.79. The upper end of that interval is the gene's LOEUF score, 0.79, which puts it in group 3 of 6, group 1 being the genes least tolerant of losing a copy. Missense variants: 525 observed, 607.82 expected, observed/expected ratio (o/e) 0.86, 90% interval 0.8 to 0.93. Synonymous variants: 219 observed, 219.59 expected, observed/expected ratio (o/e) 1, 90% interval 0.89 to 1.12.
Homologues: Orthologues: chimpanzee DENND2D (99% identical), macaque DENND2D (96% identical), rat Dennd2d (91% identical), rabbit DENND2D (90% identical), mouse Dennd2d (89% identical), pig DENND2D (89% identical), guinea pig DENND2D (89% identical), dog DENND2D (77% identical), tropical clawed frog dennd2d (57% identical), zebrafish dennd2da (53% identical), zebrafish dennd2db (49% identical). Paralogues in human: DENND2B (46% identical), DENND2A (45% identical), DENND2C (44% identical).
Diseases named in the same sentence as DENND2D in open-access papers:
DENND2D is named in the same sentence as 23 diseases in open-access papers, as found by Europe PMC text mining. Sharing a sentence is not in itself a finding about the gene and the disease. The quoted sentences say what the papers report.
hepatocellular carcinoma (7 papers, 2016 to 2024). A malignant tumor that arises from hepatocytes. "Among the DENN protein family, promoter hypermethylation-mediated the downregulation of DENND2D is associated with early recurrence of hepatocellular carcinoma and gastric cancer." (PMID 34395234, 2021). "Previous studies have shown that DENND2D acts as a tumor suppressor gene in various cancers, including hepatocellular carcinoma, non‐small cell lung cancer, and esophageal squamous cell carcinoma." (PMID 39513664, 2024). "Previous studies investigated the function of DENND2D as a tumor-suppressor gene in gastric cancer (GC), lung cancer, hepatocellular carcinoma (HCC), and bladder cancer." (PMID 35523764, 2022). "DENND2D downregulation or silencing, frequently driven by promoter hypermethylation, has been implicated in the development of non-small cell lung cancer (NSCLC), esophageal squamous cell carcinoma, hepatocellular carcinoma, and gastric cancer." (PMID 39857609, 2024). "In addition, the DENND2D mRNA expression level has been found to be significantly lower in esophageal squamous cell carcinoma tissues, hepatocellular carcinoma, lung cancers, immortalized bronchial epithelial cell lines and other precancerous lesions." (PMID 29617451, 2018).
gastric cancer (6 papers, 2014 to 2024). A primary or metastatic malignant neoplasm involving the stomach. "DENND2D is considered to act as a tumor suppressor gene and has been implicated in several types of cancer, including hepatocellular, lung, esophageal, and gastric cancer." (PMID 34589112, 2021). "DENND2D is a potential tumor suppressor in gastric cancer, and its downregulation correlates with poor prognosis and early recurrence." (PMID 39857609, 2024).
oral squamous cell carcinoma (5 papers, 2016 to 2024). "Moreover, hsa-miR-1246 suppresses the tumor suppressor gene, DENND2D, and promotes cancer metastasis and invasion in human oral squamous cell carcinoma." (PMID 36142686, 2022).
lung cancer (3 papers, 2018 to 2024). A malignant neoplasm involving the lung. "DENND2D has been proposed to suppress the tumorigenicity and proliferation of lung cancer cells." (PMID 29617451, 2018).
non-small cell lung carcinoma (3 papers, 2013 to 2022). A group of at least three distinct histological types of lung cancer, including non-small cell squamous cell carcinoma, adenocarcinoma, and large cell carcinoma. "DENND2D is also involved in the miR-522-induced migration and invasion of non-small cell lung cancer cells by targeting DENND2D." (PMID 34589112, 2021). "In a non-small cell lung cancer cell line, DENND2D was identified as a tumor-suppressor gene." (PMID 35523764, 2022). "DENND2D was shown to be down-regulated in non-small cell lung cancer and might act as a tumor-suppressor gene, and suppressed expression was observed for patients with relapses in our study." (PMID 24098497, 2013).
breast carcinoma (1 paper, 2018). "Exosomal miR-1246 can induce cell invasion and migration by regulating the DENN/MADD Domain containing 2D (DENND2D) in breast cancer cells." (PMID 29552328, 2018).
colon cancer (1 paper, 2022). "First, we knocked down DENND2D expression in the colon cancer cell lines HCT116, HT29, and SW480 by siRNA and confirmed the results by western blot assays." (PMID 35523764, 2022). "DENND2D was expressed at higher levels in normal tissue than in the tumor tissue in colon cancer (p = 0.003)." (PMID 35523764, 2022). "DENND2D expression was downregulated in CRC tissues compared with that in normal tissues in colon cancer samples from six stage IV patients." (PMID 35523764, 2022).
colorectal cancer (1 paper, 2021). A primary or metastatic malignant neoplasm that affects the colon or rectum. "By targeting BLM, DENND2D, PHLPP1 or MAOB, miR‐522 could boost tumorigenesis of colorectal cancer, non‐small‐cell lung cancer, glioblastoma and endometrial carcinoma, respectively." (PMID 33369228, 2021).
male infertility (1 paper, 2017). The inability of the male to effect fertilization of an ovum after a specified period of unprotected intercourse. "Conversely, some hypermethylated genes (such as, DENND2D and LOC401127) and hypomethylated genes (such as, HLA-DPA1 and COL18A1) have not previously been associated with male infertility, which may provide novel insight into the etiology of idiopathic SO." (PMID 28553232, 2017).
oral cancer (1 paper, 2023). "Exosomal miR-1246 from highly metastatic oral cancer cells promotes the migration and invasion of poorly metastatic oral cancer cells by downregulating the DENN/MADD-domain-containing 2D (DENND2D)." (PMID 36612314, 2023).
preeclampsia (1 paper, 2014). Preeclampsia is a hypertensive disorder of pregnancy that is characterized by new-onset hypertension with proteinuria presenting after 20 weeks of gestation, and depending on mild or severe forms may initially present with severe headache, visual disturbances, and hyperreflexia. "Furthermore, we could find only 5 genes (DAPK3, DUSP1, PAPPA2, ITCH, DENND2D) that overlapped with our gender-specific analysis of our data of all early and late combined preeclampsia samples." (PMID 25247495, 2014).
prostate carcinoma (1 paper, 2024). A carcinoma that arises from epithelial cells of the prostate gland. "As DENND2D was also implicated in the activation of interferon and inflammatory pathways in the enrichment analysis, we explored its relationship with immune cell infiltration in prostate cancer." (PMID 39857609, 2024). "Moreover, their elevated expression levels were associated with poor survival outcomes, supporting DENND2D’s potential protective role through the suppression of MYC target genes in prostate cancer progression." (PMID 39857609, 2024). "To investigate the biological role of DENND2D in prostate cancer, we identified genes that show correlated expression with DENND2D in the TCGA-PRAD dataset." (PMID 39857609, 2024). "Nonetheless, further research is needed to elucidate the precise molecular mechanisms that underpin DENND2D’s tumor-suppressive functions in prostate cancer." (PMID 39857609, 2024). "Gene set enrichment analysis revealed an association between DENND2D expression and the negative regulation of MYC target genes, including MAD2L1, ERH, and CLNS1A, which are overexpressed in prostate cancer and associated with poor survival." (PMID 39857609, 2024). "This study identified DENND2D and its genetic variant rs610261 as significant contributors to BCR risk in prostate cancer." (PMID 39857609, 2024). "While these findings advance our understanding of the role of DENND2D in prostate cancer, further research is needed to validate these results in larger cohorts and explore the therapeutic potential of targeting DENND2D in clinical settings." (PMID 39857609, 2024). "Furthermore, the elevated expression of DENND2D was associated with the enhanced infiltration of immune cells, suggesting that DENND2D contributes to prostate cancer suppression through its combined effects on oncogenic pathways and immune modulation." (PMID 39857609, 2024). "Thus, DENND2D is essential to the regulation of immune cell infiltration in prostate cancer." (PMID 39857609, 2024).
Sepsis (1 paper, 2024). Sepsis is defined as life-threatening organ dysfunction caused by a dysregulated host response to infection. "To further validate the diagnostic capability of the four genes CD160, CX3CR1, DENND2D, and FAM43A in clinical samples, we collected the 10 pairs clinical samples from the healthy and sepsis samples." (PMID 38263335, 2024). "Given DENND2D’s role as a pivotal regulator of these GTPases, it could play a significant part in the pathophysiology of sepsis." (PMID 38263335, 2024). "The qRT-PCR results exhibited that the mRNA expression of CD160, CX3CR1, DENND2D and FAM43A were obviously down-regulated in the sepsis group which was consisted with previous results." (PMID 38263335, 2024).
cancer (11 papers, 2016 to 2024). A tumor composed of atypical neoplastic, often pleomorphic cells that invade other tissues. "DENND2D is a regulator of Rab GTPases and is highly associated with carcinogenesis and the progression of cancer." (PMID 34589112, 2021). "Demethylation-based reactivation of DENND2D expression restores its tumor-suppressive function, positioning DENND2D as a potential biomarker for aggressive cancers." (PMID 39857609, 2024). "DENN/MADD domain-containing protein 2D (DENND2D) is less expressed in malignant tumors and is thought to contribute to the worsening prognosis and high recurrence rate." (PMID 35449571, 2022). "One of the molecular mechanisms resulting in cancer progression involves the direct targeting of DENND2D by miR-1246." (PMID 27929118, 2016). "Moreover, DENND2D serves as a tumor suppressor across several cancer types and disrupts MAPK signaling within tumor cells." (PMID 38263335, 2024). "DENND2D plays a crucial role in cancer proliferation and metastasis." (PMID 35523764, 2022). "Hence, downregulation of DENND2D by miR-1246 results in the acquisition of migratory and invasive abilities of poorly metastatic cancer cells in various types of cancer." (PMID 27929118, 2016).
tumor (10 papers, 2013 to 2024). "Higher expression levels of PPFIBP2 and DENND2D are known to be associated with lower levels of tumor invasiveness and a better prognosis; our present findings were consistent with these earlier observations." (PMID 34589112, 2021). "The volumes of xenografts derived from HCT116-sh1/sh2 cells were significantly larger than those from HCT116-shNC cells, whereas DENND2D overexpression significantly suppressed tumor growth." (PMID 35523764, 2022). "The DENND2D gene, another modified gene related to the immune system, has been suggested as a tumor suppressor gene." (PMID 29617451, 2018). "Subsequently, we examined the DENND2D expression level in tumor tissues and their matched normal tissues and found that DENND2D was downregulated at the mRNA level, whereas miR-522 was upregulated in tumor tissues." (PMID 26783084, 2016). "DENN/MADD domain containing 2D (DENND2D), a member of the DENND2 family, is located on chromosome 1p13.3 and encodes a 53-kDa protein that is a candidate tumor suppressor gene." (PMID 26783084, 2016). "Notably, DENND2D has also been identified as a direct target of miR-522, linking its regulation to microRNA-mediated control of tumor proliferation and metastasis in NSCLC." (PMID 39857609, 2024). "Because EBL is a bovine hematological malignancy, bta-miR-1246 may also suppress tumor suppressor genes, such as DENND2D, and may promote the progression of EBL, and could be a candidate biomarker for the development of EBL." (PMID 36142686, 2022). "In oral cancer, highly metastatic tumor cells were demonstrated to release exosomes containing miR-342-3p and miR-1246, which could be taken up by less metastatic tumor cells, resulting in an increase in their mobility and invasiveness through regulation of DENND2D." (PMID 31906022, 2019). "To determine whether DENND2D is a tumor-suppressor gene for CRC, we investigated the relationship among DENND2D expression, CRC tumorigenesis, and progression." (PMID 35523764, 2022).
infection (1 paper, 2014). The state of being infected such as from the introduction of a foreign agent such as serum, vaccine, antigenic substance or organism. "The DENND2D protein was found to be more abundant in genetically susceptible sheep following infection by H. contortus." (PMID 25074012, 2014).
DENND2D also shares sentences with these, for which no sentence is quoted: esophageal squamous cell carcinoma (4 papers); cervical cancer (1); endometrial carcinoma (1); glioblastoma (1); glioma (1); lung squamous cell carcinoma (1); melanoma (1).